GLS (glutaminase)
Diseases named in the same sentence as GLS in open-access papers (continued):
Sharing a sentence is not in itself a finding about the gene and the disease.
colorectal cancer (50 papers, 2009 to 2025). A primary or metastatic malignant neoplasm that affects the colon or rectum. "KRT20 has historically served as a diagnostic marker for colorectal carcinoma, whereas high expression of ribosomal protein L32, glutaminase, and DEAD/H box polypeptides has been associated with various cancers and metastatic lesions." (PMID 19180177, 2009). "High GLS expression in colorectal cancer has been demonstrated to result in reduced T-cell infiltration and toxicity, which is a significant factor contributing to the poor prognosis observed in patients with this condition." (PMID 40598593, 2025). "In colorectal cancer, GLS is overexpressed, and increased interaction of APC/CCDH1 and GLS by selenite treatment induces degradation of GLS that appears to contribute to inhibition of cancer progression." (PMID 37176148, 2023). "This was shown in colorectal cancer cells for a combination of glutaminase inhibitor 968 with the lysosomotropic compound chloroquine." (PMID 37255933, 2023). "Another potential biomarker characterising both colorectal cancer cells and senescent cells is the mitochondrial enzyme glutaminase 1 (GLS1) which is involved in the conversion of glutamine into glutamic acid." (PMID 36059680, 2022). "Specifically, CDK4/6 inhibition increases glutamine utilization and sensitivity to glutaminase inhibition in breast and colorectal cancer cells." (PMID 32624705, 2020). "Trials are already underway investigating the utility of Telaglenastat, a glutaminase (GLS1) inhibitor, in the treatment of several solid tumors, including metastatic renal cell carcinoma, colorectal cancer, non-small cell lung cancer, and triple-negative breast cancer." (PMID 37046766, 2023). "Therefore, HSF1 regulated DNMT3a/MIR137HG/MIR137 / GLS axis to raise glutaminolysis and mTOR activation and promote the process of colorectal cancer, and it is a potential therapeutic target for colorectal cancer." (PMID 37127605, 2023). "Furthermore, drugs targeting several amino acid metabolisms have been shown to inhibit the growth and invasion of colorectal cancer cells, for instance, the glutaminase inhibitor, CB-839, could enhance the antitumor activity of capecitabine and cetuximab." (PMID 35992263, 2022). "Here, we have systematically analyzed metabolic reprogramming in colorectal cancer cells exposed to Palbociclib, a CDKi selectively targeting CDK4/6, or Telaglenastat, a selective glutaminase inhibitor." (PMID 40696167, 2025). "In colorectal cancer, up-regulated YTHDF1 decreases the cisplatin sensitivity of cancer cells by increasing the translation of glutaminase GLS1, and inhibition of GLS1 increases the therapeutic effect of cisplatin." (PMID 38560499, 2024). "Here, we report that a combination of glutaminase inhibitor CB-839 and 5-FU inhibited the growth of PIK3CA-mutant colorectal cancers (CRCs) in xenograft, syngeneic, and genetically engineered mouse models in part through NETs." (PMID 38194275, 2024). "In colorectal cancer (CRC) cells, YTHDF1 induced cisplatin resistance by regulating glutamine metabolism through glutaminase." (PMID 35197112, 2022). "It has been reported that SIRT4 is decreased in colorectal cancer (CRC) and exerts inhibitory effects by targeting GLS-mediated AKT/GS3β/cyclin D1." (PMID 35847357, 2022). "Here, we have undertaken an in-depth, unbiased metabolomics approach to assess in greater detail the metabolic reprogramming undergone by HCT116 colorectal cancer cells exposed to either the CDK4/6i Palbociclib, the glutaminase inhibitor Telaglenastat, or their combination." (PMID 40696167, 2025). "In colorectal cancer cells, HSF1 was also found to stimulate glutaminase 1 (GLS1)-dependent mTOR activation by recruiting DNMT3a to epigenetically repress microRNA137 (MIR137) expression that targets GLS1." (PMID 39682216, 2024).
colorectal cancer (continued). "Additionally, EZH2 has been shown to regulate glutaminase (GLS) expression and promote GSH production in colorectal cancer cells, thereby protecting cells from ferroptosis under metabolic stress." (PMID 39518098, 2024). "In the present study, using MRI, we determined the correlation between glutamine uptake and the distribution of glutamine transporters, namely ASCT2 and SLC38A2 (SNAT2), glutaminase (GLS), and CSC markers, such as CD44 and CD166, in a mouse xenograft model of HT29 human colorectal cancer cells." (PMID 35365739, 2022). "Colorectal cancer models (HCT116 WT and HCT116 Bax-ko) were treated with glutaminase inhibitor CB-839 and alanine aminotransferase inhibitor L-cycloserine in order to determine the possible involvement of these enzymes in the metabolism of [19F]-fluoroglutamine." (PMID 30405205, 2018). "Furthermore, expression of glutaminolysis-related genes GLS, SLC7A11 and SLC1A5 were significantly decreased in the colorectal carcinoma cells treated with low-dose PTX." (PMID 28522974, 2017).
prostate carcinoma (48 papers, 2010 to 2025). A carcinoma that arises from epithelial cells of the prostate gland. "In this study, GLS inhibition reduced glutamine metabolism in prostate cancer cells, significantly decreasing the expression of stem cell markers (such as ALDH, OCT4, and Sox2), with the cells exhibiting reduced stemness characteristics." (PMID 41179661, 2025). "MYC functions as a central regulator of glutamine metabolism in prostate cancer by repressing miR-23a/b, thereby relieving the inhibition of mitochondrial GLS and promoting glutaminolysis, particularly in androgen-independent PC-3 cells." (PMID 41179661, 2025). "Glutamine starvation and inhibition of GLS reduced cell viability of AR-positive as well as AR-negative prostate cancer cells lines, whereby the effect on AR-negative cell lines was more pronounced in comparison to AR-positive prostate cancer cell lines." (PMID 40489535, 2025). "By decreasing the stemness of cancer cells, GLS inhibition decreases their resistance to radiation, thus enhancing the radiosensitivity of prostate cancer." (PMID 41179661, 2025). "We previously demonstrated that the switch between glutamine, an ADT-induced upregulated metabolite, and its related glutaminase isoform drives prostate cancer progression and the development of resistance to hormone therapy." (PMID 40759641, 2025). "The radiosensitizing potential of GLS inhibition with CB-839 was analyzed in prostate cancer xenograft models." (PMID 40707944, 2025). "Other studies have even found that glutaminase inhibition can overcome therapy resistance for instance in prostate cancer cells, which can be re-sensitized to radiation therapy, or methotrexate." (PMID 37255933, 2023). "A protective role of GLS-driven catabolism of glutamine is also confirmed in primary prostate cancer cells, which are sensitized to irradiation upon GLS inhibition." (PMID 36768660, 2023). "The druggability of prostate cancer glutamine metabolism is more readily achievable with our greater understanding of tumor metabolism and the advent of selective glutaminase inhibitors that have proven safe and tolerable in early-phase clinical trials." (PMID 36959101, 2023). "Numerous studies imply that the upregulation of GLS plays a critical role in tumor proliferation in various types of cancers, including glioma, lymphoma, non-small cell lung cancer, prostate cancer, and TNBC." (PMID 36139432, 2022). "CB-839 inhibition of GLS resulted in substantial radiosensitization in prostate cancer cell cultures, lowering the stemness properties of prostate cancer cells." (PMID 34359941, 2021). "Of particular interest in this research, direct repression of miRNA-23a and miRNA-23b by c-Myc is responsible for increased expression of GLS protein in human Burkitt lymphoma and prostate cancer." (PMID 33610185, 2021). "Recent reports of metformin combined with a glutaminase inhibitor suggested a synergistic effect in pancreatic and prostate cancers." (PMID 32158544, 2020). "Moreover, the synthesis of glutathione driven by glutaminase (GLS) also plays a significant role in the survival and radioresistance of prostate cancer CSCs." (PMID 40422220, 2025). "Glutamine metabolic reprogramming not only sustains tumor proliferation but also contributes to therapy resistance; inhibition of GLS or MYC sensitizes prostate cancer cells to radiotherapy, while autophagy enables glutamine-independent cells to withstand metabolic stress." (PMID 41179661, 2025). "Glutaminase (GLS) driven glutamine catabolism may promote radiosensitivity of prostate cancer by regulating redox status, dryness, and ATG5-mediated autophagy." (PMID 39588377, 2024). "We suggest that inhibitors of the GTωA pathway, which will interfere with closure of the last step of the methionine salvage pathway, may exhibit synergistic or added efficacy with other anti-glutaminase pathway drugs against prostate cancer and other cancers." (PMID 37627015, 2023).
prostate carcinoma (continued). "Finally, a different metabolic need boosts GLS-mediated glutamine catabolism in an interesting prostate cancer cell model in which stemness and epithelial–mesenchymal transition (EMT) properties are uncoupled." (PMID 36768660, 2023). "Moreover, it was also found that CSCs of a patient with radioresistant prostate cancer had a high glutamine demand due to overexpression of GLS induced by the transcription factor MYC." (PMID 34359941, 2021). "Inhibition of GLS with BPTES or genetic silencing of GLS/GLS2 genes increases radiation sensitivity in lung and prostate cancer cell lines." (PMID 41179661, 2025). "In AR-positive LNCaP prostate cancer cells, 5α-dihydrotestosterone (DHT) significantly increased the expression levels of ASCT2 and glutaminase (GLS), the enzyme responsible for the deamination of glutaminase to glutamate." (PMID 40489535, 2025). "In PC3 prostate cancer (PCa) models, MYC elevates glutaminolysis by indirectly enhancing translation of glutaminase 1 (GLS1), via inhibiting the GLS1 repressors, miR-23a/b." (PMID 37450923, 2024). "In prostate cancer treated with androgen deprivation therapy, suppressed GLS1 expression compensated for the expression of the isozyme glutaminase C, which limited therapeutic efficacy." (PMID 39061847, 2024). "In human prostate cancer, MYC drove glucose metabolism via the suppression of TXNIP (a potent negative regulator of glucose uptake), which was predominantly dependent on the glutaminase-MondoA axis." (PMID 37626036, 2023). "It has been shown that glutamine deficiency or inhibition of key regulators of glutamine metabolism, such as GLS and the transcription factor MYC, leads to prostate cancer radiosensitization." (PMID 36771124, 2023). "In previous studies, GLS and PDHA1 were found to play a synergistic role in promoting glutamine dependence in prostate cancer patients." (PMID 36588699, 2022). "GLS and PDHA1 played a synergistic role in promoting greater glutamine dependence in prostate cancer patients." (PMID 35937995, 2022). "Here, we measured αKG levels upon glutaminase inhibitor treatment in vivo and found that both DON treatment and CB-839 treatment significantly reduced intracellular αKG levels in prostate cancer xenograft tumors." (PMID 29107960, 2017). "In a similar manner, GLS expression is higher in prostate cancer cells (e.g., LNCaP, 22Rv1, DU145, and PC-3) as compared with non-malignant prostate epithelial cells (e.g., RWPE-1), and selective inhibition of GLS reduced proliferation and survival." (PMID 35127483, 2021). "The present work shows the presence of enzymes of both the GLS1 and the glutaminase II pathways in stromal cells in human prostate cancer, but not in normal human prostate." (PMID 31861280, 2019). "In P493 Burkitt's lymphoma and PC3 prostate cancer cell lines, c-Myc upregulates GLS through an indirect mechanism involving transcriptional repression of micro-RNAs miR-23a/b, which target the 3′-UTR of the GLS transcript and suppress its translation." (PMID 27089238, 2016). "Numerous evidence implicates that upregulation of KGA, especially GAC (jointly referred to as GLS henceforth), plays a critical role in tumor proliferation throughout various types of cancers, such as glioma, lymphoma, non-small cell lung cancer, prostate cancer, and triple-negative breast cancer." (PMID 32937954, 2020).
ovarian carcinoma (45 papers, 2014 to 2025). A malignant neoplasm originating from the surface ovarian epithelium. "By further evaluating the clinical significance of the ratio of GLN catabolism to anabolism, it was found that ovarian cancer patients with high GLS protein expression were associated with lower overall survival compared with patients having high GLUL protein expression." (PMID 36523985, 2022). "Furthermore, GLS overexpression is associated with poor survival and it is associated with platinum resistance in ovarian cancer." (PMID 32974128, 2020). "The disruption of this metabolic cycle by simultaneous targeting glutamine synthase in CAFs and glutaminase in cancer cells was shown to reduce the tumor growth in an ovarian cancer mouse model." (PMID 39456684, 2024). "IPN60090 was initially developed as an inhibitor of glutaminase-1 (GLS-1), and it has entered clinical trials for cancer therapy, especially for lung and ovarian cancers." (PMID 38383406, 2024). "For instance, it has been observed that treatment with the glutaminase inhibitor 968 along with anti-PD-L1 reduced the intraperitoneal dissemination of ovarian cancers." (PMID 37233659, 2023). "The expression of glutaminase, which breaks down Gln, was higher in highly aggressive ovarian cancer cells." (PMID 36523985, 2022). "The mTOR inhibitor rapamycin can strongly inhibit the phosphorylation of S6 and the expression of GLS, and Gln promotes the proliferation of ovarian cancer cells through the mTOR/S6 pathway." (PMID 36523985, 2022). "Most studies have shown that the critical target of platinum resistance related to glutamine metabolism is GLS; knock out of GLS can resensitize platinum-resistant ovarian cancer cells to cisplatin, and overexpression of GLS can lead to platinum resistance." (PMID 36523985, 2022). "It has been reported that the transfection of ovarian cancer cells with RPS6-siRNA reduces the activities of glutaminase (GLS) and glutamate dehydrogenase (GDH), leading to a reduction in glutamine-induced proliferation of the cells." (PMID 35008473, 2021). "Inhibition of GLS—a downstream target of c-MYC—by CB-839 sensitizes ovarian cancer cells to PARP inhibition and prolong survival in tumor-bearing mice." (PMID 33718147, 2021). "The CAF-derived Gln was exported to the ovarian cancer cells and converted to glutamate by the enzyme glutaminase." (PMID 34373744, 2021). "The treatment of paclitaxel or cisplatin resistant ovarian cancer cells with a glutaminase inhibitor increased their sensitivity to chemotherapy through inhibiting cell proliferation, regardless of their glutamine dependence status." (PMID 32708822, 2020). "Eventually, ovarian cancer cisplatin-resistant cells were shown to rely on MYC-dependent glutaminase upregulation to catabolize glutamine and fuel OXPHOS." (PMID 32932943, 2020). "The expression of glutaminase 1 (GLS1) was enhanced in metastatic glutamine-dependent ovarian cancer cells and targeting GLS1 using siRNA sensitized the cancer cells to cisplatin." (PMID 32708822, 2020). "This investigation found that GLS was associated with a very poor prognosis in patients with breast, blood, soft tissue, and ovarian cancer—the overexpression of GLS was highly positively correlated with low survival." (PMID 30871151, 2019). "The combination of platinum and the GLS inhibitor BPTES was markedly more effective than either agent alone in cisplatin sensitive or resistant human ovarian cancer cell lines." (PMID 27191653, 2016). "Consistent with this, we demonstrated that the effective inhibition of c-Myc with 10058-F4 in human ovarian cancer cell lines correlated with reduced glutaminase and ASCT-2 protein levels and subsequently reduced radiolabeled glutamine uptake." (PMID 27191653, 2016). "Increased uptake of glutamine was also dependent on autophagy and dramatically sensitized cultured ARHI-expressing ovarian cancer cell lines to glutaminase inhibition." (PMID 27784287, 2016).